POSTN (periostin)
Description:
Induces cell attachment and spreading and plays a role in cell adhesion. Enhances incorporation of BMP1 in the fibronectin matrix of connective tissues, and subsequent proteolytic activation of lysyl oxidase LOX (By similarity).
Synonyms: PN; OSF-2; OSF2; PDLPOSTN
Tractability: Small molecule: a structure with a bound ligand is known. Antibody: UniProt places it where antibodies can reach, with high confidence; its Gene Ontology location is reachable by antibodies, with high confidence; UniProt predicts a signal peptide or a membrane-spanning region.
Gene: Protein-coding gene on chromosome 13 (37,562,582 to 37,598,855, reverse strand). Ensembl gene ENSG00000133110.
Subcellular location: Golgi apparatus; Secreted; Secreted, extracellular space, extracellular matrix
Subcellular location (Human Protein Atlas): Golgi apparatus; Predicted to be secreted
Gene Ontology:
Molecular function: metal ion binding; protein binding; cell adhesion molecule binding; extracellular matrix structural constituent; heparin binding
Biological process: cell adhesion; cellular response to vitamin K; extracellular matrix organization; homophilic cell-cell adhesion; bone regeneration; cellular response to fibroblast growth factor stimulus; cellular response to transforming growth factor beta stimulus; cellular response to tumor necrosis factor; negative regulation of cell-matrix adhesion; negative regulation of substrate adhesion-dependent cell spreading; neuron projection extension; positive regulation of chemokine (C-X-C motif) ligand 2 production; positive regulation of smooth muscle cell migration; regulation of systemic arterial blood pressure; response to estradiol; response to hypoxia; response to mechanical stimulus; response to muscle activity
Cellular component: extracellular matrix; extracellular region; trans-Golgi network; Golgi apparatus; non-collagenous component of basement membrane; non-collagenous component of interstitial matrix; neuromuscular junction
Genetic constraint (gnomAD): Loss-of-function variants: 44 observed, 70.97 expected, observed/expected ratio (o/e) 0.62, 90% interval 0.49 to 0.8. The upper end of that interval is the gene's LOEUF score, 0.8, which puts it in group 3 of 6, group 1 being the genes least tolerant of losing a copy. Missense variants: 743 observed, 821.32 expected, observed/expected ratio (o/e) 0.9, 90% interval 0.85 to 0.96. Synonymous variants: 287 observed, 284.47 expected, observed/expected ratio (o/e) 1.01, 90% interval 0.92 to 1.11.
Homologues: Orthologues: macaque POSTN (98% identical), chimpanzee POSTN (97% identical), dog POSTN (96% identical), pig POSTN (95% identical), rabbit POSTN (91% identical), rat Postn (90% identical), mouse Postn (90% identical), guinea pig POSTN (75% identical), tropical clawed frog postn (69% identical), zebrafish postnb (53% identical), zebrafish postna (51% identical), Drosophila melanogaster Fas1 (17% identical), and 1 more. Paralogues in human: TGFBI (36% identical).
Diseases named in the same sentence as POSTN in open-access papers:
POSTN is named in the same sentence as 448 diseases in open-access papers, as found by Europe PMC text mining. Sharing a sentence is not in itself a finding about the gene and the disease. The quoted sentences say what the papers report.
asthma (248 papers, 2012 to 2026). "Periostin is a biomarker associated with airway inflammation and remodeling, key components of asthma pathophysiology." (PMID 41567689, 2026). "For instance, serum periostin, a biomarker commonly used to identify T2 asthma, has differing diagnostic value depending on ethnicity, age or asthma severity." (PMID 41602869, 2026). "In contrast, in a 17-centre prospective cohort study of infants with severe bronchiolitis, serum periostin induced by type 2 inflammatory cytokines (e.g., interleukin IL-4 and IL-13) was associated with asthma risk by age 6 years." (PMID 40852413, 2025). "This study evaluated serum periostin as a diagnostic biomarker and explored multidimensional phenotypes in adult asthma." (PMID 41374409, 2025). "Multidimensional clustering highlights clinically relevant phenotypes linked to periostin, inflammatory burden, and lung function, supporting its role in personalized asthma management." (PMID 41374409, 2025). "While periostin’s utility as a diagnostic biomarker for asthma is well supported, its performance for disease severity stratification remains inconsistent across studies." (PMID 41374409, 2025). "Periostin expression in the epithelium is increased by the T2-cytokine, IL-13, and in asthma has been associated with both increased airway eosinophils and mucus secretion." (PMID 40133927, 2025). "Serum periostin demonstrates potential as a diagnostic biomarker for adult asthma in a South Indian cohort, showing high sensitivity and specificity." (PMID 41374409, 2025). "Despite corticosteroid treatment, elevated serum periostin levels and increased bronchial epithelial cell proliferation are associated with more frequent asthma exacerbations and persistent eosinophilic airway inflammation." (PMID 38474348, 2024). "Using this assay, sputum periostin was detectable and associated with more disease-relevant parameters in asthma than serum periostin." (PMID 36763690, 2023). "They examined the association of periostin levels at entry with the development of asthma at 6 years of age." (PMID 36694181, 2023). "POSTN has been linked with various diseases, including atopic dermatitis, asthma, and the progression of multiple cancers." (PMID 38020106, 2023). "On the contrary, our analysis found a protective association between nasal periostin detection and current asthma at age 4 years, ever diagnosis of asthma, maintenance asthma treatment prescription, and admissions for recurrent wheezing." (PMID 36694181, 2023). "POSTN encodes for periostin, a secreted extracellular matrix protein that contributes to airway remodeling, a crucial pathophysiological feature of asthma." (PMID 36776870, 2023). "After adjusting for confounding factors, they found that, compared to the low periostin group, the asthma risk was significantly higher among infants in the intermediate group but non-significantly greater in the high-level group." (PMID 36694181, 2023). "By contrast, we found a protective association between nasal periostin detection and current asthma at 4 years, ever diagnosis of asthma, maintenance asthma treatment prescription, and respiratory admissions." (PMID 36694181, 2023). "The unadjusted risk of current asthma at 4 years in infants with detectable nasal periostin was half that of children in whom periostin was undetected (OR: 0.522; CI 95% 0.303–0.899)." (PMID 36694181, 2023). "Periostin induces hypersecretion of type 2 inflammatory factors and mucus production, and is associated with asthma, allergic rhinitis and CRS." (PMID 37046572, 2023). "For example, it has been shown in previous studies that asthma is associated with an increase in serum periostin levels in children and in a meta-analysis study, it has been reported that periostin has moderate accuracy in diagnosing asthma." (PMID 37173720, 2023).
asthma (continued). "It is worth noting that ours is the second study to analyse the association between periostin in infants with bronchiolitis and the development of asthma later in life, and the results are contradictory." (PMID 36694181, 2023). "The secondary endpoints are time from baseline to drop-out caused by loss of asthma control, changes in serum-periostin, blood-eosinophils, FeNO, Forced Expiratory Volume in 1 s (FEV1) and in sputum-eosinophils." (PMID 37794472, 2023). "Results in the same direction have been found with respect to serum periostin, which was positively associated with asthma symptoms and Th2 mediators." (PMID 36287905, 2022). "The expression pattern of periostin splicing variants has been reported in cerebral ischemia, asthma, MI, IPF, retinal ischemia, pIBD, joint, and serum." (PMID 36611844, 2022). "In patients with asthma, CRSwNP and EoE, dupilumab treatment was associated with rapid, sustained reductions in serum levels of periostin versus placebo." (PMID 34037993, 2021). "ALOX15 (genetic loci: 17p13.2) and POSTN (genetic loci: 13q13.3) genes were hypomethylated in the nasal epithelium and associated with asthma." (PMID 34566492, 2021). "Periostin is most prominently linked to asthma with reports on its expression and involvement in the development and repair of lung tissue." (PMID 34512647, 2021). "In a clinical study, serum periostin has been evaluated to identify patients who are more effective with biologics and is at risk of developing asthma exacerbation and decreased lung function." (PMID 34439751, 2021). "Consistent with previous studies on patients with asthma and the general population, the present study showed that the serum periostin level was negatively associated with BMI, albeit marginally." (PMID 32517742, 2020). "Subgroup analysis showed patients with high periostin level (>50 ng/ml) had a lower risk of asthma exacerbation after receiving anti-IL-13 treatment (MD = -0.30, 95%CI: -0.41–0.19, P<0.001)." (PMID 30703143, 2019). "Our results showed that reduced asthma exacerbation rate was significantly associated with high periostin level (>50 ng/ml) in patients’ serum." (PMID 30703143, 2019). "Periostin has been associated with asthma severity and increased levels of periostin have been found in the serum of children with exacerbated manifestations of asthma." (PMID 31214165, 2019). "A prognostic relationship between periostin and risk of asthma exacerbations has been observed in clinical studies." (PMID 30937129, 2019). "Subgroup analysis showed patients with high periostin level had a lower risk of asthma exacerbation after receiving anti-IL-13 treatment." (PMID 30703143, 2019). "Serum periostin has been associated with persistent eosinophilic airway inflammation in asthma and higher frequency of asthma exacerbations." (PMID 30308057, 2018). "Previous data found that elevated levels of serum periostin in adults with asthma are associated with fixed and more severe airflow obstruction, and greater lung function decline." (PMID 30598830, 2018). "Serum periostin is a marker of type 2 inflammation, and has a stronger association with airways eosinophilia in severe asthma than blood eosinophil levels and FeNO." (PMID 28194189, 2017). "Elevated serum levels of periostin have been associated with asthma activity and severity, and with the presence of late-onset eosinophilic asthma." (PMID 29176991, 2017). "Periostin is an extracellular matrix protein that is associated with eosinophilic airway inflammation and the severity of asthma." (PMID 28219384, 2017). "Asthma patients carrying the G allele at −1508A>G had significantly higher serum levels of periostin, myeloperoxidase, and urinary levels of 15-hydroxyeicosatetraenoic acid and sphingosine-1-phosphate (P = 0.016, P = 0.027, P = 0.032, and P = 0.010, resp)." (PMID 28659663, 2017).
asthma (continued). "Periostin is a biomarker indicating the presence of type 2 inflammation and submucosal fibrosis; serum periostin levels have been associated with asthma severity." (PMID 28219384, 2017). "Periostin levels are associated with airway eosinophilia and are suppressed by corticosteroid treatment in asthma." (PMID 27130294, 2016). "Serum periostin can be considered a systemic biomarker Th2-high asthma related because it is a signature molecule associated to higher AHR, serum IgE, eosinophilic inflammation, subepithelial fibrosis, compared to Th2-low asthma." (PMID 26430389, 2015). "Periostin is potentially relevant in the pathogenesis of asthma-associated inflammation and its phenotypes." (PMID 25981515, 2015). "Herein we explore the biological role of periostin in asthma using a mouse model and periostin deficient mice." (PMID 22093101, 2012). "Previous studies have suggested that GLP-1RA therapy is associated with lower periostin levels in a cross-sectional cohort with asthma and T2DM, which may reflect a reduction in airway inflammation and remodeling processes." (PMID 41567689, 2026). "Elevated periostin also correlates with asthma exacerbation risk and may serve as a marker of ongoing airway remodeling." (PMID 41374409, 2025). "Additionally, it was effective in reducing exacerbation rates, but only in patients with severe asthma exhibiting high levels of periostin, a biomarker associated with early T2high asthma." (PMID 41145900, 2025). "Additionally, Periostin has been associated with persistent and severe asthma, while IL-13 has been recognized as a key regulator of asthma chronicity in murine models." (PMID 40503233, 2025). "This suggests that periostin was more closely associated with atopy than with asthma." (PMID 39534447, 2024). "Given the emerging roles of TSLP and periostin as diagnostic markers in conditions like asthma and obstructive lung disease, it is anticipated that I3C may exert multifaceted therapeutic effects against various diseases, including allergic skin inflammation." (PMID 39722037, 2024). "The expression of POSTN is associated with chronic inflammatory diseases, such as heart failure, diabetic retinopathy, asthma, allergic conjunctivitis, chronic sinusitis/chronic rhinosinusitis with nasal polyps, and atopic dermatitis, which are increasingly being observed." (PMID 39272982, 2024). "The severity of asthma may be associated not only with the number of eosinophils but also with the serum periostin level." (PMID 38999820, 2024). "High values of serum-periostin are associated with T2 asthma." (PMID 37794472, 2023). "For this reason, periostin quantification could help in the identification of patients with severe uncontrolled asthma and those susceptible to anti-IL-13 therapy." (PMID 37762787, 2023). "Notably, AEC and NEC-derived correlated gene signatures including CCL26, CLCA1 and POSTN were involved in IL-13 signaling, where IL-13 signaling of the airway epithelium is associated pathophysiology of asthma and airway inflammation." (PMID 37438356, 2023). "We studied expression of innervation markers: ubiquitin carboxy-terminal hydrolase L1 (UCHL1/PGP9.5) and occludin (OCLN) as well as genes reported to be associated with asthma: periostin (POSTN), galectin-3 (LGAL3), secretory leukocyte protease inhibitor (SLPI), IL-4, IL-5, IL-13, IL-17." (PMID 35534846, 2022). "Furthermore, it is well known that high serum periostin can be a marker for predicting the effect of biological therapy in asthma or AD patients and a prognostic marker for assessing the risk of asthma exacerbation." (PMID 34439751, 2021). "Periostin is a matricellular protein that plays important physiologic and pathogenic roles in skin fibrosis and serves as a biomarker for several known Th2-associated diseases (e.g. AD, asthma, nasal polyps, systemic sclerosis)." (PMID 33329590, 2020).
asthma (continued). "Interestingly, several recent studies on asthma and the general population have revealed that serum periostin was negatively associated with body mass index (BMI) and serum leptin." (PMID 32517742, 2020). "Periostin promotes adhesion and migration of epithelial cells and is associated with CRSwNP and asthma." (PMID 32292784, 2020). "There have been several studies reporting that periostin was associated with poor asthma control." (PMID 30937129, 2019). "The associations of EGF and Periostin with adult-onset asthma were positive but weak." (PMID 31217483, 2019). "Additionally, periostin has been postulated to be a potential diagnostic marker for asthma and is involved in many aspects of allergic inflammation, including the development of a Th2 immune response." (PMID 31776238, 2019). "This is similar to the approach we took in our asthma studies in which we initially identified a type 2 high asthma molecular phenotype based on airway gene expression, and then expanded this work to identify the best associated biomarkers (periostin, eosinophils, FeNO)." (PMID 30383540, 2019). "Furthermore, previous reports suggested that high serum periostin is associated with asthma severity." (PMID 30473714, 2018). "Secondly, we found enhanced serum periostin levels in asthma patients carrying the −1508G allele." (PMID 28659663, 2017). "Serum periostin has been shown as an emerging biomarker of T helper type 2 (Th2)-driven inflammation, which is strongly associated with airway eosinophilia in severe asthma." (PMID 28429138, 2017). "The aim of this study is to evaluate, in a pilot fashion, whether patients with moderate asthma and higher baseline levels of serum periostin show a greater risk of exacerbation during a year of follow-up." (PMID 27965769, 2016). "This pilot study aims at evaluating whether in patients with moderate asthma, higher baseline levels of serum periostin are associated with a greater risk of exacerbation." (PMID 27965769, 2016). "Similarly, reports also show that serum periostin levels are associated with airway eosinophilia in asthma." (PMID 27130294, 2016). "Periostin can also reduce the symptoms associated with asthma." (PMID 25981515, 2015). "It examined associations between asthma exacerbations requiring systemic corticosteroids over 2 years and clinical and genetic factors in patients with the type 2–low endo-genotype, defined by serum periostin levels lower than 95 ng/mL and the IL4RA rs8832 A allele." (PMID 40687950, 2025). "Furthermore, higher serum periostin levels in RW-impacted preschoolers are reported to be associated with an increased risk of acute wheezing attacks in the following year and risk of developing asthma at school-age." (PMID 36776870, 2023). "Periostin is present in the thickened basement membrane and in the serum of asthmatic patients, especially those with eosinophilic airway inflammation and atopy, and also induces the hypersecretion of type 2 inflammatory factors, mucus production associated with asthma, allergic rhinitis and CRS." (PMID 37046572, 2023). "Periostin is an extracellular matrix protein produced by airway epithelial cells and fibroblasts upon activation by IL-4 or IL-13, which is implicated in tissue remodeling and correlated with lung function decline as well as asthma exacerbations (despite high-dose ICS therapy)." (PMID 37035303, 2023). "Interestingly, we observed that treatment with systemic corticosteroids was associated with lower periostin levels, while those on montelukast had higher IL-6 in plasma, independently from the asthma severity and other potential confounders, including age, BMI, or co-morbidities." (PMID 28429138, 2017). "Therefore, targeting the actions of periostin may help elucidate the underlying molecular mechanisms of asthma and may represent a promising strategy for the development of effective therapeutic agents for the treatment of asthma." (PMID 25981515, 2015).